CRP (C-reactive protein)
Diseases named in the same sentence as CRP in open-access papers (continued):
Sharing a sentence is not in itself a finding about the gene and the disease.
infection (continued). "This is of the utmost importance since spinal infections are not necessarily accompanied by increased C-reactive protein (CRP) or fever, which are expected in other types of infection, rendering imaging extremely important in differentiating from non-infectious causes." (PMID 39336911, 2024). "Anti-infection treatment may also affect NLR, and the lack of data on other inflammation indicators, such as CRP and IL-6, is another limitation." (PMID 37457569, 2023). "First-line laboratory evaluation should include a complete blood count (CBC) with differential, comprehensive metabolic panel, inflammatory markers with C-reactive protein (CRP) and erythrocyte sedimentation rate (ESR), and stool evaluation to rule out infection." (PMID 36986830, 2023). "However, analyses showed overall patients diagnosed with infection had significantly elevated WCC and CRP despite similar MELD scores compared to those not diagnosed and twice the in-hospital mortality rate, which support the likely validity of this diagnosis." (PMID 36407574, 2023). "Colistin could be stopped within 72 h of initiation in almost half of infection episodes (18/41; 43.9%) in the CRE culture-negative group, following receipt of laboratory results such as a low CRP (< 10 mg/L) or negative BC." (PMID 36756243, 2023). "The values of PCT and CRP collected on the day of infection diagnosis were compared to those collected on day 11 after ICU admission, the median time for infection occurrence, in patients without secondary infection." (PMID 37887237, 2023). "Combining the CRP level and NLR did not improve the detectability of infections either." (PMID 37761321, 2023). "After the observation that HIPEC can elevate postoperative CRP levels in absence of infection and suppress WBC counts in response to infection, we next explored whether these effects depend on the HIPEC protocol." (PMID 36631814, 2023). "When differentiating between viral infections and no infection, IMX-BVN-2 showed an AUC value of 0.82–0.83, whereas PCT, CRP, and white blood cell count could not differentiate between these groups (AUC <0.4)." (PMID 36941681, 2023). "C-reactive protein testing (CRP POCT) offers a quick and reliable indicator to better understand the seriousness of an infection, more specifically to understand if an infection is self-limiting or not, and thus to assess if antibiotic treatment would provide any additional benefit to the patient." (PMID 37324137, 2023). "However, the serum C-reactive protein, IL-6, PCT level of infection-related group were significantly higher than that of noninfectious RP-DPLD patients (all p<0.05)." (PMID 37408612, 2023). "Similarly to other reports, MLR was described to correlate to disease activity, ESR, and CRP and to be increased in SLE compared to controls but to not differentiate between SLE patients with and without infection." (PMID 37893155, 2023). "Unfortunately, CRP and ESR remained at high levels and the infection could not be controlled after microbial culture results oriented antibiotics treatment." (PMID 36936762, 2023). "CRP, PCT or IL-6 alone could not be used to determine whether the patients with culture-negative BALF had infection." (PMID 36237436, 2022). "Serum infection markers such as ESR, CRP, and blood cell count are not equivalent to wound status." (PMID 35884890, 2022). "For the patient with infection after ACL reconstruction (Case 12), after thorough and radical open debridement, followed by long-term antifungal treatment, the patient had no sign of relapse, and the CRP and ESR had returned to normal levels." (PMID 36506031, 2022). "While 16 of 26 patients (62%) with probable infection, 5 of 8 patients (63%) with possible infection and 71 of 84 patients (84%) without shoulder PJI had a normal (< 10 mg/l) serum CRP level, only 1 of 18 patients (6%) with definitive infection had a normal CRP level." (PMID 33515325, 2022).
infection (continued). "However, host-response-based single-biomarker tests such as C-reactive protein (CRP), pro-calcitonin (PCT), and lactate are often non-specific for the type of infection and can be elevated in the inflammatory response to non-infection settings such as trauma." (PMID 36543117, 2022). "As opposed to other inflammatory biomarkers such as CRP, PCT was ordered less frequently with the majority of our database having only a single baseline PCT value, which raises the possibility of a missed rise in PCT with early infection." (PMID 35025929, 2022). "P2X7 correlated with CRP, a finding supported by previous studies, but not with ferritin, denoting that the shedding of the P2X7 receptor is somehow related to the IL-6/CRP inflammatory programme in both bacterial and SARS-CoV-2 viral (this study) infections." (PMID 35663992, 2022). "Second, the current review did not include more factors affecting post-PCNL infection, such as IL-6, PCT, CRP, stone load, amount of hemoglobin drop, size of the puncture channel, amount of bleeding, amount of intraoperative lavage, and renal perfusion pressure." (PMID 36515726, 2022). "However, positive correlations of C18:1 ceramide with CRP and of C16:0 ceramide with D‐dimer were observed in both groups, suggesting that these differences might arise from some fundamental factors related to infection by a pathogen, rather than disease severity." (PMID 36214754, 2022). "Using the elevated levels of CRP and AGP helps in capturing infection missed out by the maternal reported symptoms as well as asymptomatic infants, who show no symptoms but have subclinical infection." (PMID 36211493, 2022). "The excessive uncontrolled inflammatory responses mainly led by IL-6, IFNγ, TNFα, CRP, D-dimer, VES, and the lack of vitamin D (pre-hormone D) were common clinical traits of this infection, though those parameters were common to other types of lung diseases and infections." (PMID 36428884, 2022). "According to the present data, increasing values of sTREM-1, PCT, and CRP can lead to a diagnosis of IA in pediatric patients without other etiologic agents of infection, and increasing in LDH and sTREM-1 levels present the severity of the infection and death." (PMID 35752831, 2022). "Laboratory examinations were performed to rule out infection and inflammatory disease; the white blood cell (WBC) count and erythrocyte sedimentation rate (ESR), as well as C-reactive protein (CRP), uric acid, and rheumatoid factor levels, were within their normal ranges." (PMID 34260526, 2021). "According to the results of clinical manifestations and laboratory examination including WBC, CRP, and ESR, after first-stage debridement and custom-made bone cement intramedullary nail operation, all the 19 cases achieved infection control and there was no infection recurrence during the follow-up." (PMID 33748280, 2021). "Furthermore, the D+T− and D+T+ groups were subdivided into secondary infection and no-secondary infection groups to analyze differences in PCT and CRP kinetics and calculate detection accuracy of these biomarkers for the occurrence of a secondary infection." (PMID 34353339, 2021). "In our previous study, we also found that PCV-vaccinated patients who once obtained a breakthrough infection had a significantly higher lowest WBC, lower neutrophils, lower lymphocytes, and lower CRP values than non-vaccinated patients, indicating a less severe clinical disease." (PMID 34579280, 2021). "In addition, C-reactive protein (CRP) and creatine kinase (CK) were also elevated in the severe and critical cases, which had complications, including ARDS but not secondary infection." (PMID 35011632, 2021). "We described time-dependent limits for the interpretation of five biomarkers (PSEP, PCT, CRP, WBC, and IL-6), which can be used as acceptable values in uncomplicated patients without infection after major surgery, including patients after kidney, liver, and pancreas transplantation." (PMID 33505219, 2021).
infection (continued). "Conversely, C-reactive protein (CRP) and procalcitonin (PCT) are the most widely used markers to guide antibiotic therapy, although their early increase after birth is not always related to the onset of infections." (PMID 33525647, 2021). "In addition, the CRP and ESR can increase in the presence of an inflammatory process even in the absence of infection." (PMID 35003964, 2021). "According to previous studies, CRP and PCT do not detect SBI well at the very beginning of the infection, so their sensitivity and negative predictive value may decrease." (PMID 33663442, 2021). "In conclusion, it is important to consider pregnancy-specific reference values as elevations of CRP and PTX3 during the later phase may occur in absence of infection." (PMID 34408755, 2021). "CRP and ESR values are nonspecific markers that could be elevated in various conditions, such as infection and systemic autoimmune diseases." (PMID 33243164, 2020). "Although it was not a specific aim of our study, we also analyzed the relationship between inflammatory markers and the final diagnosis of infection and found significantly higher values of CRP and ESR in patients with OM compared to patients without any infection." (PMID 32486304, 2020). "Considering that the LRG and CRP values were not significantly different between the CAM-f(−) group and the control group, we combined these two groups into one group (termed as “no fetal infection”) to compare with the CAM-f(+) group (“fetal infection”)." (PMID 33211747, 2020). "Additionally, the CTP and MELD scoring, CRP concentration, monocyte count, AAR, and NLR had moderate abilities to discriminate patients with or without infection." (PMID 32155772, 2020). "However, CRP and ESR are inflammatory markers with a low sensitivity: levels within the normal range do not rule out infection." (PMID 31641803, 2020). "During this period, CRP remained around 0.5 mg/dl and did not fluctuate so much, so it may be that P-SEP is superior in the evaluation of the residual infection focuses." (PMID 31139474, 2019). "Acute phase proteins, such as C-reactive protein (CRP), Serum Amyloid A2 (SAA2), and Lipopolysaccharide binding protein (LPS-BP) were increased several fold in both infection types, but were not present at high enough levels to be quantitated in the naive NHP plasma samples." (PMID 30774579, 2019). "There was no improvement in AUC for CRP and ESR in combination for infection." (PMID 31208975, 2019). "C-reactive protein (CRP): An elevated CRP > 60 mg/L demonstrated very high specificity for SBP (96.5%) in one study, but likely represents overall inflammatory response to infection, rather than specificity for SBP over other sources of infection." (PMID 29721399, 2018). "Measuring serum concentrations of CRP and SAA may help the clinician to differentiate doubtful cases of normal postoperative variation from early postoperative infection without the need of more invasive, expensive, or time-consuming tests." (PMID 29784055, 2018). "Indeed, the investigated inflammatory marker—C-reactive protein (CRP) indicated the presence in most of the subjects of chronic inflammation, although no clinical evidence of infection was observed." (PMID 29019951, 2017). "Patients with elevated CRP and WBC had no signs of infection." (PMID 28660216, 2017). "However, the timing of the second stage was variable but essentially depended on the resolution of infection as evident by improved hip mobility, absent clinical signs of infection, and ESR and CRP levels returning to normal values." (PMID 29021886, 2017). "The most widely studied markers of post-stroke infection—procalcitonin (PCT), C-reactive protein (CRP), and white blood cells (WBC)—have only shown moderate predictive value, and their levels do not increase early enough to be of help before the infection is clinically apparent." (PMID 28701906, 2017).
infection (continued). "Canonical inflammatory markers such as circulating levels of CRP and WBC, on the other hand, appear to primarily reflect surgical trauma, without enabling identification of the presence of infection and cannot be used for determining the presence or absence of infection." (PMID 25793700, 2015). "While CRP and WBC again lacked any discriminatory power in identifying the presence of infection, PSP levels proved to be significantly higher in patients with infection in the adjusted analysis (p = 0.015)." (PMID 25793700, 2015). "Moreover, in univariate logistic regression analysis PSP at day 2 significantly predicted the clinical outcome postoperative infection (OR = 2.5, p = 0.001), while canonical biomarkers for infection (WBC, CRP) lacked any discriminatory ability in this regard." (PMID 25793700, 2015). "In a prospective cohort of unselected patients undergoing cardiac surgery, we set out to elucidate the diagnostic accuracy of serum PSP levels as opposed to canonical biomarkers (CRP, WBC) of inflammation to discriminate between the presence of infection and surgical trauma." (PMID 25793700, 2015). "This might be because CRP and SIRS subscores are markers that may be elevated in inflammation without infection." (PMID 25460569, 2014). "The correlation between CRP, PCT, and renal function was analyzed in patients without infection." (PMID 25407928, 2014). "Many inflammatory mediators and acute phase reactants, like C-reactive protein (CRP) and procalcitonin, have been described as reliable markers of infection; however none are specific enough, since they are also increased in non-infectious inflammatory conditions." (PMID 20920231, 2010). "Serum inflammatory markers such as C-reactive protein (CRP) are widely used as a supplementary tool in the therapeutic follow-up of infected patients, alongside clinical diagnosis and microbiological (and histological) confirmation of infection, although no clinical thresholds exist on that matter." (PMID 40565868, 2025). "We hypothesized that elevated CRP is common after PROM, even in the absence of infection." (PMID 41441318, 2025). "However, according to previous studies, inflammatory biomarkers such as C-reactive protein and procalcitonin may not be useful in identifying secondary infections in severely ill patients with SARS-CoV-2, similar to patients without infection." (PMID 39540054, 2024). "Further analysis using the ROC curve found that the AUC of IL‐6 to distinguish the effectiveness of anti‐infection at 12 h was 0.895, whereas PCT and CRP were failed to predict the antimicrobial efficacy, which may be associated with the unique characteristics of these three biomarkers." (PMID 38967137, 2024). "However, the CRP and WBC as biomarkers of infection were not routinely elevated in this cohort." (PMID 38726020, 2024). "For example, a study evaluating changes in CRP and ESR levels prior to infected prosthesis explantation and periprosthetic tissue debridement and after 6 weeks of targeted antibiotic therapy found that the decrease in CRP and ESR levels did not consistently predict infection recurrence." (PMID 38761247, 2024). "Unlike the short pentraxin C reactive protein (CRP), whose expression is mostly confined to the liver, PTX3 is made by several immune and non-immune cells at sites of infection and inflammation, where it intercepts fundamental aspects of infection immunity, inflammation, and tissue remodeling." (PMID 37885881, 2023). "Additionally, several studies have documented the sensitivity of serial CRP levels in monitoring SSI following fracture fixation as well as in lumbar spine surgery but none of them have correlated the CRP and WBCs count in patients without infections." (PMID 37872533, 2023).
infection (continued). "Early fever and high levels of CRP and inflammatory cytokines IL-6, TNF-α, and IFN-γ, as seen in our LE patients in the absence of infection, strongly resemble cytokine release syndrome, which may result in multiorgan dysfunction involving the brain, lung, and kidney." (PMID 37626859, 2023). "Interestingly, unlike CRP, serum levels of PCT, IL-6, and IL-10 in the GN-BSI group were consistently higher than those in the GP-BSI group at all time points during 48 h post-infection." (PMID 37986183, 2023). "The non-survivors also exhibited higher markers for infection-related clinical complications, such as international normalized ratio (INR), D-dimer, urea, total bilirubin, alkaline phosphatase (ALK), creatinine, c-reactive protein (CRP), and serum ferritin levels (all p < 0.05)." (PMID 36614820, 2022). "Evaluation of white blood cell count (WBC) and C-reactive protein levels (CRP) in 75 patients with transoral thyroid surgery showed a transient WBC increase postoperatively, that returned to basic value within one week after surgery and without any clinical sign of infection." (PMID 36561507, 2022). "Although our data demonstrated declining CRP and WBC values prior to reimplantation regardless of infection persistence, similar to previous documentations, analysis could not reveal any significant differences in these values that could help guide reimplantation." (PMID 36139954, 2022). "Compared with the non-infection group, the infection group was younger; more likely to receive general surgery, mechanical ventilation, and type II surgical incision; had longer hospital and ICU stays; and had higher levels of the nCD64 index, CRP, and PCT (all p < 0.05)." (PMID 36522701, 2022). "ESR testing was insensitive for identifying infection, our study also showed that ESR could not also improve the accuracy for identifying PJI on the basis of CRP, whether it is used alone or combined with other blood markers, which is in line with previous studies." (PMID 35453256, 2022). "In addition, we had intended to measure inflammatory markers of zinc status (CRP and AGP) so that PZC adjustments for the presence of infection could be undertaken, however this was not possible for technical reasons." (PMID 35118107, 2021). "However, CRP suffers from low specificity in diagnosing patients with systemic inflammation, and variation in early PCT levels is dependent on the type and severity of the initial infection and not necessarily on the severity of the disease itself." (PMID 33692779, 2021). "C-reactive protein (CRP) is a sensitive but non-specific marker of systemic inflammation and is primarily produced by hepatocytes under transcriptional control by IL-6 in response to infection, trauma, surgery, burns, tissue infarction, advanced cancer, and chronic inflammatory conditions." (PMID 34361836, 2021). "CRP, an acute phase response protein upregulated in response to bacterial infections, and FCP, a cation-binding protein released by granulocytes in response to infection, were not anticipated to be reduced during active QBECO treatment given its mechanism of action." (PMID 31380382, 2019). "Similarly, although many biomarkers, e.g., C-reactive protein and procalcitonin (PCT) to name just two, have been suggested to help diagnosis or to rule out infection, none is specific for infection and all can be altered in other conditions that commonly affect ICU patients." (PMID 27184564, 2016). "However, the CRP level is not always elevated in SLE patients with infection at initial admission, and it may increase in SLE flare-up patients without infection." (PMID 26273660, 2015). "We hypothesized that CRP is a sensitive but non-specific marker of developing complications after esophagectomy, while PCT is a more specific marker of developing severe post-operative infections." (PMID 25663633, 2015).